SPHK1 (sphingosine kinase 1)
Diseases named in the same sentence as SPHK1 in open-access papers (continued):
Sharing a sentence is not in itself a finding about the gene and the disease.
kidney damage (1 paper, 2020). "The increase of SphK1 expression in this kidney damage model was consistent with a previous finding that overexpression of SphK1 in transgenic mice produced heart fibrosis." (PMID 32393187, 2020). "Given the important regulatory role of S1P in immune response and inflammation, we determined whether SphK1 gene deletion attenuated the inflammatory process thereby the kidney damage in DOCA-salt kidneys." (PMID 32393187, 2020). "The present study examined the role of endogenous SphK1 in the kidney damage in deoxycorticosterone acetate (DOCA)-salt-treated mice, a hypertensive model with kidney damage, using SphK1 knockout (KO) mice." (PMID 32393187, 2020). "The findings from our current study demonstrated that SphK1 deletion protected the kidney without altering DOCA-salt hypertension, suggesting that SphK1/S1P pathway may also participate in RPP-induced kidney damage." (PMID 32393187, 2020).
leishmaniasis (1 paper, 2020). Infectious disease that is transmitted through the bite of hematophagous female phlebotomine sand flies. "Notably, in the case of infectious diseases like leishmaniasis, a reduced level of phosphorylated SphK-1 with deregulated S1P signaling was reported that could be corroborated with the disease pathology." (PMID 32195246, 2020).
leukoaraiosis (1 paper, 2012). "The process of leukoaraiosis was doubled in SphK1−/− LPS treated animals (4.4±0.33) compared to wild type LPS treated group (2.4±0.33), **p<0.0001." (PMID 22615770, 2012).
liver cirrhosis (1 paper, 2021). "SphK1 was noted to be highly expressed in serum exosomes from liver cirrhosis patients, which encouraged the migration of LX-2 (p < 0.01)." (PMID 34054552, 2021).
liver failure (1 paper, 2025). A liver disease characterized by the liver losing or has lost all of its function. "Indeed, in LPS/D-galactosamine (D-Gal)-induced liver failure, S1P levels were elevated, whilst the expression of SphK1, S1PR1, and S1PR3 was upregulated in the liver, and the levels of serum markers of liver failure, AST and ALT, and the serum cytokines TNF-α, IL-1, and IL-6 were increased." (PMID 39935473, 2025).
malignant mesothelioma (1 paper, 2012). A malignant neoplasm of the pleura or peritoneum, arising from mesothelial cells. "The lipid kinase SphK1 plays a positive and essential role in the growth and development of malignant mesothelioma and is therefore a likely therapeutic target." (PMID 23028939, 2012). "To test our hypothesis that SphK1 is an effective novel therapeutic target in malignant mesothelioma, we investigated multi walled nanotubes (MWNT)-induced granulamatous inflammation in control and SphK1−/− mice." (PMID 23028939, 2012).
mantle cell lymphoma (1 paper, 2022). Mantle cell lymphoma is a rare form of malignant non-Hodgkin lymphoma affecting B lymphocytes in the lymph nodes in a region called the ``mantle zone''. "Modulation of SLs, particularly S1P by SPHK1, has been also linked to the alteration of the NKT immune response against mantle cell lymphoma (MCL) cells." (PMID 36361536, 2022).
mastocytosis (1 paper, 2018). A clonal myeloproliferative neoplasm characterized by the proliferation and accumulation of neoplastic mast cells in one or multiple organs or organ systems. "To further assess the potential effectiveness of these inhibitors in preclinical models, we first treated bone marrow cells from four different patients with indolent and smoldering mastocytosis with SPHK1-1 or SPHK2-I." (PMID 29643855, 2018). "Similarly, we found an increase in the expression of SPHK1 and SPHK2 in mastocytosis MC lines (i.e., LAD2 and HMC-1) compared with normal HuMCs, which was variable depending on the donor." (PMID 29643855, 2018).
meningococcal infection (1 paper, 2023). Infections with bacteria of the species neisseria meningitidis. "Western Blot analysis showed, that SphK1 protein levels were increased and p(Ser-225)-SphK1 was only detectable in the plasma membrane fraction after infection, indicating increased phospho-activation and translocation of SphK1 upon meningococcal infection." (PMID 38033162, 2023).
neural tube defect (1 paper, 2014). A congenital defect characterized by failure of the neural tube to close completely; this results in the presence of openings in the brain or spinal cord. "We examined the incidence of neural tube defects and weight changes of fetus and placenta, as well as the gene expression of LASS5 (in maternal liver and fetus), Sphk1, Sphk2, Sgpl1, and Sgpp1 in the maternal liver, uterus, fetus, and placenta." (PMID 25383881, 2014).
neuroendocrine tumors (1 paper, 2023). "Overexpression of SPHK1 promotes the progression of multiple neuroendocrine tumors." (PMID 38027207, 2023).
parasite (1 paper, 2020). "This reduced level could be due to the degradation of host SphK-1 during parasite infection, as transcriptional regulation could not be accounted in erythrocytes due to lack of protein translation machinery." (PMID 32195246, 2020).
periodontitis (1 paper, 2023). An acute or chronic inflammatory process that affects the tissues that surround and support the teeth. "Additionally, the SPHK1 protein expression was upregulated in gingival tissue samples from participants with periodontitis compared to healthy controls, suggesting that there are alterations in S1P metabolism in the context of periodontitis." (PMID 37108099, 2023).
peritoneal mesothelioma (1 paper, 2012). A benign or malignant mesothelial neoplasm that arises from the peritoneum. "Using a multi-walled carbon nanotubes induced peritoneal mesothelioma mouse model, we showed that the SphK1−/− null mice exhibited significantly less inflammation and granulamatous nodules compared to their wild type counterparts." (PMID 23028939, 2012).
pheochromocytoma (1 paper, 2015). "In agreement with a role for cAMP, forskolin has been shown to activate Sphk1 in pheochromocytoma cells years ago42." (PMID 25832730, 2015). "Forskolin has been shown to activate Sphk1 in pheochromocytoma cells." (PMID 25832730, 2015).
Pleural effusion (1 paper, 2016). The presence of an excessive amount of fluid in the pleural cavity. "However, cancer cells originating from pleural effusion with metastatic characteristics including MDA-MB-231 increased SphK1 expression in stiff substrates and increased S1P secretion." (PMID 26877098, 2016).
pneumonia (1 paper, 2019). An acute, acute and chronic, or chronic inflammation focally or diffusely affecting the lung parenchyma, caused by an infection in one or both of the lungs (by bacteria, viruses, fungi, or mycoplasma.). "Enhanced SPHK1 expression was also observed in macrophages in inflamed murine and human lungs in pneumonia, while genetic SPHK1 deletion protected mice from pneumonia-induced hyperpermeability." (PMID 31379883, 2019).
psychosis (1 paper, 2018). "In summary, the three newly identified genes (MACROD2, RAC1, and SPHK1) are related to brain functions and have plausibility for involvement in the pathophysiology of psychosis." (PMID 29695761, 2018).
pterygium (1 paper, 2019). A wedge-shaped fibrovascular lesion arising from the bulbar conjunctiva and extending to the cornea. "As UV irradiation induces significant S1P production and the expression of S1P2 was particularly significant in pterygium tissue, we analyzed the mRNA expression levels of SphK 1 and 2 by qRT-PCR to determine whether SphK is expressed in UV-NCFCs compared to NCFCs." (PMID 31547113, 2019).
renal carcinoma (1 paper, 2021). A carcinoma arising from the epithelium of the renal parenchyma or the renal pelvis. "However, Gao and Smith (2011) reported contrasting results in which knockdown of SphK2 led to increased S1P production in renal carcinoma cells owing to the elevated expression of SphK1." (PMID 33968977, 2021).
retinal degeneration (1 paper, 2019). Degeneration of the retina. "Next, we evaluated the role of SphK1 and the resulting suppression of S1P synthesis in light-induced retinal degeneration in mice using a SphK inhibitor." (PMID 31357484, 2019). "Second, we examined the role of SphKs in light-induced retinal degeneration only with a SphK inhibitor that was not selective for SphK1 or SphK2." (PMID 31357484, 2019).
salivary gland carcinoma (1 paper, 2010). A carcinoma that arises from the major or minor salivary glands. "The current study was to characterize the expression of SPHK1 in salivary gland carcinomas (SGC) and to investigate the association between SPHK1 expression and progression of SGC." (PMID 20846391, 2010).
skin cutaneous melanoma (1 paper, 2022). "For example, PD-1 (encoded by PDCD1) and PD-L1 (encoded by CD274), a well-defined immunosuppressive axis in the TME, were found to be correlated with SPHK1 expression in most cancer types, including skin cutaneous melanoma (SKCM)." (PMID 36050478, 2022).
skin squamous cell carcinoma (1 paper, 2021). A carcinoma arising from the squamous cells of the epidermis. "Sphingosine kinase 1 (SphK1) is overexpressed in skin squamous cell carcinoma (SCC)." (PMID 33465049, 2021).
streptococcal pneumonia (1 paper, 2024). A febrile disease caused by streptococcus pneumoniae. "Recent work showed that Streptoccocus pneumoniae induced SPHK1 expression and S1P production in human macrophages, and that Sphk1 deficiency ameliorated lung injury in a mouse model of streptococcal pneumonia." (PMID 38385743, 2024).
subarachnoid hemorrhage (1 paper, 2014). A serious neurological disorder characterized by intracranial hemorrhage into the subarachnoid space. "Isoflurane delays the development of early brain injury following subarachnoid hemorrhage through upregulating SPHK1 expression." (PMID 25069764, 2014).
thyroid follicular carcinoma (1 paper, 2013). "A series of studies confirm that SphK1 enhances cell migration in human thyroid follicular carcinoma cells (ML-1)." (PMID 24970177, 2013).
uveal melanoma (1 paper, 2022). A melanoma derived from melanocytes of the uveal tract. "Specifically, in uveal melanoma, overexpression of both SPHK1 and SPHK2—the enzymes that catalyze the production of S1P—is associated with worse or unfavorable disease outcomes compared to the low-expression groups." (PMID 35565311, 2022).
Venous thrombosis (1 paper, 2025). Formation of a blood clot (thrombus) inside a vein, causing the obstruction of blood flow. "To further investigate the functional role of SPHK1 in thrombus fibrosis, we employed a rat model of venous thrombosis established by inferior vena cava (IVC) ligation, and administered the selective SPHK1 inhibitor PF543 via intraperitoneal injection." (PMID 41333463, 2025).
cancer (307 papers, 2006 to 2026). A tumor composed of atypical neoplastic, often pleomorphic cells that invade other tissues. "SphK1 is more prominently implicated in cancer progression and chemoresistance, while SphK2, although involved in cell death and survival pathways, appears to function differently depending on the cellular context." (PMID 40427516, 2025). "In this study, we focused specifically on SphK1, the sphingosine kinase predominantly implicated in cancer and investigated the combinatorial effect of forced FAM46C expression and treatment with PF-543, a selective SphK1 inhibitor." (PMID 40427516, 2025). "SphK1 inhibitors are considered potential drugs since SphK1 is often upregulated in cancer and associated with different processes of tumorigenesis." (PMID 39940821, 2025). "In fact, H3K27ac deposition is increased in many genes associated with cancer hallmarks, such as the negative regulation of apoptosis (e.g., sphingosine kinase 1, SPHK1), or components implicated in inflammatory signaling, including TNF-α and IFN pathways." (PMID 39000179, 2024). "SPHK1 is often upregulated in cancer, and high levels of SPHK1 have been associated with tumor invasion, angiogenesis, and resistance to radio- and chemotherapy." (PMID 36672428, 2023). "There is a consensual agreement that SphK1 and S1P expression is elevated in UC and colon-associated cancers." (PMID 35158806, 2022). "Sphk1 is widely upregulated across a diverse range of human cancers and has been inextricably linked to tumorigenesis." (PMID 35854233, 2022). "By utilizing integrative analysis, SPHK1 has been associated with immune features across multiple cancer types and positively correlated with programmed cell death ligand 1 (PD-L1, also known as B7-H1/B7 Homolog1 or CD274)." (PMID 36050478, 2022). "Since SPHK1 activation is associated with cancer development with poor prognosis, the ability of fingolimod in inhibiting SPHK1 is quite intriguing and needs further investigations." (PMID 35250559, 2022). "Overexpression of sphingosine kinase 1 (SphK1) is casually associated with many types of cancer, and inhibitors of SphK1 sensitize tumors to chemotherapy." (PMID 36532885, 2022). "Odds ratios (ORs) and 95% CIs were combined to assess the association between SPHK1 expression and clinicopathological characteristics of cancer patients." (PMID 35126792, 2022). "SPHK1 has been established as an oncogene, and its overexpression is associated with a poor clinical prognosis in most cancers." (PMID 34207383, 2021). "High expression of SPHK1 has been observed in various tumor types and is associated with poorer clinical prognosis and shorter overall survival in cancer patients." (PMID 34820423, 2021). "SPHK1 has been linked to acquired drug resistance of various cancers to chemotherapeutics and receptor inhibitors." (PMID 34207383, 2021). "In the context of cancer, SPHK1 is the main isoform that is functionally associated with the hallmarks of cancer, which has been universally recognized as a key player of oncogenesis." (PMID 34820423, 2021). "Some have linked such anti-cancer effects to its abilities in inducing proteasomal and lysosomal degradation of SPHK1." (PMID 34820423, 2021). "At the cellular level, the primary biological actions of SphK1 are to promote cell proliferation, migration and survival and to inhibit apoptosis, and thus upregulation of SphK1 is often associated with cancer progression, metastasis and a poor prognosis." (PMID 33633691, 2020). "Up-regulation of SphK1 in acute colitis and colitis-associated cancer leads to an increased production of S1P." (PMID 32456134, 2020). "Sphingosine kinase 1 (SphK1) has recently gained attention as a potential drug target for its association with cancer and other inflammatory diseases." (PMID 31822735, 2019). "SphK1 upregulation has been identified in several cancers and is associated with poor survival prognosis." (PMID 31809267, 2019).
cancer (continued). "Previous studies have demonstrated that S1P and SPHK1 are associated with lymphatic metastasis in various types of cancer including breast, gastric, colon, liver and ovarian cancer." (PMID 30018456, 2018). "Under condition of severe hypoxia, SphK1 promotes the Warburg effect, the cancer associated metabolic adaptation to low oxygen condition that is the essential survival mechanism for cancer cells to produce ATP and protect against reactive oxygen species (ROS)." (PMID 29385066, 2018). "Reversely, inhibition, mutation or silence of SphK1 will lead to cancer cell apoptosis and tumor repression." (PMID 28206952, 2017). "SPHK1 is also associated with malignant transformation and cancer proliferation, among other functions that are linked to cell survival, which are corroborated by findings in MCF-7 cells." (PMID 29186783, 2017). "The following section presents an updated overview on how SphK1 and 2 isozymes and isoforms are linked to carcinogenesis, development of resistance to cancer treatment and new cancer therapeutic targets." (PMID 28869494, 2017). "Targeting S1P signaling by SPHK2 dysfunction significantly suppressed cancer development in the mouse model of colitis-associated cancer, whereas SPHK1 inhibition reduced peritumoral lymphatic density and LN metastases." (PMID 28804221, 2017). "On the other hand in cancer associated with inflammation in contrast to oncogenic SphK1, either overexpression or down-regulation of SphK2 has been shown to inhibit cell growth and promote apoptosis in a cell-dependent manner." (PMID 29216917, 2017). "We have shown that SphK1 is linked with chronic intestinal inflammation to colitis-associated cancer in a mouse model." (PMID 29269995, 2017). "Overexpression of SphK1 is linked to oncogenicity through various mechanisms such as imbalance of SphK1/S1P, enhancing oncogene Ras, promoting cancer stem cell proliferation to increase tumorigenesis, and imbalance between intracellular and extracellular S1P." (PMID 28869494, 2017). "A potential anticancer mechanism of FTY720 is through the inhibition of sphingosine kinase 1, a proto-oncogene with in vitro and clinical cancer association." (PMID 27036015, 2016). "SphK1 is overexpressed in various cancers, and the upregulation of SphK1 is associated with poor prognosis in many types of human cancers." (PMID 26673009, 2016). "An accumulating amount of data suggests that SPHK1 is associated with processes that are involved in cancer progression, such as cell oncogenesis, survival, metastasis and the neovascularization of the tumor microenvironment." (PMID 27811359, 2016). "Augmentation of SPHK1 has been widely reported in many cancer cells, as it serves as a hallmark of angiogenic properties of the tumors." (PMID 27284992, 2016). "FTY720 inhibits sphingosine kinase 1, a proto-oncogenic enzyme with in vitro and clinical cancer association." (PMID 27036015, 2016). "Accumulating evidence has suggested that SPHK1 is involved in processes associated with cancer progression, including cell transformation, survival, and migration, metastasis, and tumor microenvironment neovascularization." (PMID 26311741, 2015). "SPHK1, in particular, has been implicated in oncogenic roles in cancer, including proliferation, resistance to apoptosis and transformation." (PMID 25153718, 2014). "Current evidence indicates that selection for high SPHK1 in cancer is driven both by oncogenic driver mutations and by environmental pressures such as hypoxia." (PMID 24970218, 2014). "SphK1 and SphK2 have both been implicated in tumorigenesis; however, there is much less evidence for SphK2 involvement in cancer." (PMID 23028939, 2012). "Additional evidence also suggested that tumor cells can overexpress Sphk1, implicating the S1P pathway in the uncontrolled growth and dampening of cell death associated with cancers." (PMID 22096531, 2011).